MIR550B1 (microRNA 550b-1)
Synonyms: hsa-mir-550b-1
Gene: MicroRNA gene on chromosome 7 (30,289,794 to 30,289,890, reverse strand). Ensembl gene ENSG00000283237.
Gene Ontology:
Biological process: miRNA-mediated post-transcriptional gene silencing
Cellular component: RISC complex
Homologues: Orthologues: chimpanzee ptr-mir-550-1 (100% identical), macaque mml-mir-550 (64% identical).